EZH1 (enhancer of zeste 1 polycomb repressive complex 2 subunit)
Diseases named in the same sentence as EZH1 in open-access papers (continued):
Sharing a sentence is not in itself a finding about the gene and the disease.
malignant thyroid tumours (2 papers, 2017 to 2020). "This novel finding notwithstanding, not all toxic adenomas display an EZH1 mutation and from screening of other benign and malignant thyroid tumours it appears that EZH1 mutations at least in codon 571 are not principally involved in regulation of proliferation in these tumours." (PMID 32303903, 2020).
psoriasis (2 papers, 2020 to 2025). An autoimmune condition characterized by red, well-delineated plaques with silvery scales that are usually on the extensor surfaces and scalp. "At the beginning of our study, we have detected the level of EZH1 mRNA in psoriasis lesional skin." (PMID 33011750, 2020). "Our analysis showed differential expression of EED, EZH1/2, and RBBP4 in the PRC2 complex, likely to affect stem cell self-renewal and possibly contributing to keratinocyte hyperproliferation in psoriasis." (PMID 40650108, 2025).
thyroid cancer (2 papers, 2017 to 2025). "Previous studies have reported that EZH1 Q571R mutations are associated with increased H3K27me3 levels, and that EZH1 mutation–induced H3K27me3 overexpression correlates with tumor aggressiveness and dedifferentiation in thyroid carcinoma." (PMID 41090246, 2025).
thyroid tumor (2 papers, 2022 to 2025). A benign or malignant neoplasm affecting the thyroid gland. "In thyroid tumors, EZH1 seems to be associated with oncocytic tumorigenesis, with frequencies of 20% and 10% in oncocytic adenomas and carcinomas, respectively." (PMID 41090246, 2025).
Weaver syndrome (2 papers, 2016 to 2023). Weaver syndrome (WVS) is a rare, multisystem disorder characterized by tall stature, a typical facial appearance (hypertelorism, retrognathia) and variable intellectual disability. "Similarly, in humans, heterozygous partial loss-of-function variants in EZH2 increase skeletal growth in Weaver syndrome, whereas, in mice, homozygous loss of Ezh1 and Ezh2 impairs growth plate function by inhibiting proliferation and hypertrophy of growth plate chondrocytes." (PMID 36927955, 2023). "Furthermore, individuals with Weaver syndrome show tall stature due to increased skeletal growth, whereas, in mice, deletion of Ezh1/2 leads to diminished skeletal growth." (PMID 27897169, 2016). "Our data suggest that the mutations causing Weaver syndrome are not simple loss-of-function mutations because, in mice, heterozygous—or even homozygous—loss-of-function mutations in Ezh2 do not have a skeletal phenotype unless Ezh1 is also ablated." (PMID 27897169, 2016).
astrocytoma (1 paper, 2013). "CBX6, CBX7 and EZH1 shared a similar pattern and correlated negatively with increasing astrocytoma grade, whereas the opposite occurred with EZH2 and PHF19." (PMID 24260522, 2013). "Interestingly, changes in EZH2, PHF19, CBX7, CBX6 and EZH1 occurred progressively as astrocytoma grade increased." (PMID 24260522, 2013). "Among them, the expressions of EZH2 and PHF19 correlated positively with the astrocytoma grades, whereas the expressions of CBX7, CBX6 and EZH1 correlated negatively with astrocytoma grades." (PMID 24260522, 2013).
breast tumors (1 paper, 2025). "All PRC2 components, except for EED and EZH1, were significantly enriched in breast tumors compared to normal tissues." (PMID 41413688, 2025).
cardiomyopathy (1 paper, 2023). A disease of the heart muscle or myocardium proper. "Significant differential imbalance between all four phenogroups was found for several SNPs located in genes with known cardiomyopathy links other than DCM such as posterior myocardial infarction, the top 5 hits were EZH1, NIBAN1, C7, CDIN1, and ADPRHL1." (PMID 36631531, 2023).
diabetes (1 paper, 2018). "The finding that PRC2 loss triggers diabetes-mimicking transcriptional dysregulation and dedifferentiation warrants deeper investigations into relative Ezh1-, Ezh2- and non-methyltransferase-dependent Polycomb activities in the β cell compartment." (PMID 29754954, 2018).
gastric cancer (1 paper, 2025). A primary or metastatic malignant neoplasm involving the stomach. "TRIM21 overexpression significantly enhances apoptosis and inhibits stem cell properties in GC cells; moreover, TRIM21 can inhibit EZH1 (an enhancer of zeste homolog 1) stability to improve gastric cancer apatinib therapy." (PMID 40936722, 2025).
Hürthle cell adenomas (1 paper, 2021). "EZH1 mutations were found in 20% of Hürthle cell adenomas and 10% of Hürthle cell carcinomas, and 53.8% of the mutations were Y642F." (PMID 34054720, 2021).
intellectual disabilities (1 paper, 2025). "In 2019, a genetic analysis of recessive intellectual disabilities (IDs) uncovered a homozygous truncating EZH1 variant (NM_001991: p.Leu80Serfs*6) as the candidate cause of ID in two siblings born from healthy consanguineous parents." (PMID 41153408, 2025).
liver disease (1 paper, 2020). "Loss of H3K27me3 marks in human liver disease has been associated with increased transcription of genes associated with tumorigenesis, consistent with the association of Ezh1/2 loss with liver pathology seen in our Ezh1/2-KO mouse model." (PMID 32428001, 2020). "Here, we used male and female Ezh1/Ezh2 double knockout (E1/E2-KO) mice to address these questions by investigating the requirement of Ezh1 and Ezh2 for sex-biased gene regulation in mouse liver, and to discover any sex-dependent effects of Ezh1/Ezh2 loss on genes associated with liver disease." (PMID 32428001, 2020). "Here, we use an Ezh1-knockout mouse model with a hepatocyte-specific knockout of Ezh2 to investigate the role of H3K27me3 in regulating sex-biased gene expression in mouse liver, and the potential impact of this regulation on sex-biased susceptibility to liver disease." (PMID 32428001, 2020). "Thus, our findings highlight the potential role of sex differences in histone modifications catalyzed by Ezh1/Ezh2 in widespread sex differences in liver diseases." (PMID 32428001, 2020).
Malignant Rhabdoid Tumor (1 paper, 2025). "Dual inhibition of EZH1/2 is also one of the promising therapeutic approaches for SMARCB1-deficient tumors worth exploring in future clinical practice.EZH1 and EZH2 contribute to the growth of MRT (Malignant Rhabdoid Tumor) cells and H3K27 methylation." (PMID 40115023, 2025).
meningioma (1 paper, 2020). A generally slow growing tumor attached to the dura mater. "An interesting finding was that the fastest growing cranial meningioma (P6_C1) carried one-copy loss of ARID1A and SMARCE1, the subunits of SWI/SNF, and one-copy gain of SUZ12 and EZH1, the components of PRC2." (PMID 32724039, 2020).
myeloid neoplasm (1 paper, 2023). Proliferation of myeloid cells originating from a primitive stem cell. "Other histone methylating genes, such as KMT5B/EZH1/KMT2D/KMT2E/SETD5, were also included in brown module, and related to pathological process or prognosis of myeloid neoplasms (MDS/AML)." (PMID 37953918, 2023).
myocardial infarction (1 paper, 2021). Gross necrosis of the myocardium, as a result of interruption of the blood supply to the area, as in coronary thrombosis. "In mice, Ezh1 was required for neonatal heart regeneration after myocardial infarction and overexpression of Ezh1 promoted heart regeneration by upregulating cardiac muscle growth genes." (PMID 33618656, 2021).
non-small cell lung carcinoma (1 paper, 2020). A group of at least three distinct histological types of lung cancer, including non-small cell squamous cell carcinoma, adenocarcinoma, and large cell carcinoma. "Interestingly, miR-17 has been identified to target enhancer of zeste homolog 1 (EZH1) and downregulates its expression, sensitizes non-small cell lung cancer cells to erlotinib." (PMID 33143661, 2020).
pancreatic cancer (1 paper, 2021). "Given the report, a future study is also required to determine whether EZH1 also contributed to the modulation of TPH1 and 5-HT7 pathways in pancreatic cancer cells." (PMID 34771469, 2021).
periodontitis (1 paper, 2022). An acute or chronic inflammatory process that affects the tissues that surround and support the teeth. "In summary, we identified eight SNPs associated with periodontitis and highlighted the possible mechanisms of EZH1." (PMID 36611863, 2022). "Furthermore, TWAS and in silico analyses illustrated that EZH1, genes co-expressed with which were significantly enriched in cell-substrate junction and other important pathways, may contribute to the risk of periodontitis." (PMID 36611863, 2022). "EZH1 was identified as a novel susceptibility gene for periodontitis by TWAS and was significantly upregulated in periodontitis-affected gingival tissues." (PMID 36611863, 2022). "Further differential expression analysis revealed that EZH1 was consistently upregulated in periodontitis sites among patients with periodontitis." (PMID 36611863, 2022). "Altogether, the GO and KEGG enrichment analysis results provide additional evidence for the potential role of genes co-expressed with EZH1 in the pathological process of periodontitis." (PMID 36611863, 2022). "To address the pathogenesis of EZH1 in periodontitis, we also explored the genes co-expressed with EZH1." (PMID 36611863, 2022). "Interestingly, EZH1 and MRPS23 were newly identified, whereas previous studies have verified SIGLEC14 and SIGLEC5 as genetic risk factors for periodontitis." (PMID 36611863, 2022). "Notably, the expression of the newly identified gene EZH1 increased in periodontitis sites in both GEO datasets." (PMID 36611863, 2022). "Thus, genes correlated with EZH1 may play a role in cell and extracellular matrix interactions and participate in the development of periodontitis." (PMID 36611863, 2022). "Furthermore, EZH1 was significantly upregulated at periodontitis sites." (PMID 36611863, 2022). "Therefore, EZH1 may participate in the development of periodontitis through inflammation." (PMID 36611863, 2022). "Finally, we identified two previously reported genes (SIGLEC5, SIGLEC14) and two novel genes (EZH1, MRPS23), proving that TWAS is a supplemental strategy for studying periodontitis’ etiology." (PMID 36611863, 2022).
renal cell carcinoma (1 paper, 2021). "It is reported that EZH1 promotes renal cell carcinoma proliferation and is used as a prognostic indicator and therapeutic target." (PMID 33796460, 2021).
Respiratory insufficiency (1 paper, 2016). "Ezh1/2 mice showed increased mortality at ∼2 weeks of age of apparent respiratory insufficiency." (PMID 27897169, 2016).
schizophrenia (1 paper, 2021). A major psychotic disorder characterized by abnormalities in the perception or expression of reality. "Moreover, H3K27 methyltransferase EZH1 expression has been reported to be increased in PFC of schizophrenia subjects." (PMID 34930904, 2021).
Sepsis (1 paper, 2024). Sepsis is defined as life-threatening organ dysfunction caused by a dysregulated host response to infection. "Later, the authors will increase the sample size to further investigate the exact mechanism of circRBM33/miR-15a-5p/EZH1 axis in sepsis-induced ALI." (PMID 39667201, 2024). "As predicted by the bioinformatics website starBase 3.0, miR-15a-5p targets EZH1 which has a binding site for miR-15a-5p, and EZH1 in ALI was determined by RT-qPCR and Western Blot, and it was found in the plasma of patients with sepsis and in MLE-12 cells with a high expression of EZH1." (PMID 39667201, 2024).
skin tumor (1 paper, 2025). "The skin tumor was histologically identical to In‐N and exhibited mutations, including EZH1 Y642F, KRAS G60R, and TERT‐p C228T, which were also identified in In‐N." (PMID 41090246, 2025). "The skin tumor resembled STc of the primary TFND and harbored EZH1, KRAS and TERT promoter mutations." (PMID 41090246, 2025). "Molecular analysis revealed EZH1 mutations in both the Out‐N and STc of TFND, while KRAS and TERT promoter mutations were restricted to STc and the skin tumor." (PMID 41090246, 2025). "The EZH1 Y642F mutation was detected in all tumor samples with variant allele frequency (VAF) 36.1%, 37.9%, and 18.9% in Out‐N, In‐N, and skin tumor, respectively." (PMID 41090246, 2025).
status epilepticus (1 paper, 2015). Status epilepticus is defined as a continuous seizure lasting more than 30 min, or two or more seizures without full recovery of consciousness between any of them. "Here, we explored the transcriptional response of genes associated with polycomb repressive complex (PRC) 1 (Ring1A, Ring1B, and Bmi1) and PRC2 (Ezh1, Ezh2, and Suz12), as well as additional transcriptional regulators Sirt1, Yy1, and Yy2, in a mouse model of status epilepticus (SE)." (PMID 25806020, 2015).
teratoma (1 paper, 2017). A non-seminomatous germ cell tumor characterized by the presence of various tissues which correspond to the different germinal layers (endoderm, mesoderm, and ectoderm). "To examine the differentiation potential of these cells, we injected EZH1−/− or EZH2−/− H1 hESCs into immuno-deficient mice and monitored teratoma formation." (PMID 28939884, 2017). "However, on the basis of H&E staining of the teratoma sections, we did not observe any ectoderm tissue from teratomas formed from EZH1−/− or EZH2−/− H1 cells." (PMID 28939884, 2017).
Thyroid adenoma (1 paper, 2025). The presence of a adenoma of the thyroid gland. "Other alterations include TSHR, GNAS, and EZH1 mutations in hyperfunctioning thyroid adenomas and wnt pathway dysregulation in cribriform morular carcinoma." (PMID 41175860, 2025). "EZH1 mutations are typically found in combination with TSHR or GNAS mutation and occur in approximately 30% hyperfunctioning thyroid adenomas." (PMID 41175860, 2025).
thyroid nodule (1 paper, 2019). A small circumscribed mass in the THYROID GLAND that can be of neoplastic growth or non-neoplastic abnormality. "The reason was probably a small cohort of benign samples, because mutations in the EZH1 gene were detected almost 20 times more frequently (13.5 vs 0.7%) in benign than in malignant thyroid nodules." (PMID 31085772, 2019).
viral infection (1 paper, 2021). "Next, we conducted loss-of-function assays for EZH1 and EZH2 using lentivirus-mediated shRNA in Huh7 and HepG2 cells, successfully achieving stable knockdown of EZH1 and EZH2 using RFP and EGFP as a viral infection marker, respectively." (PMID 34725436, 2021).
cancer (37 papers, 2012 to 2026). A tumor composed of atypical neoplastic, often pleomorphic cells that invade other tissues. "Although these drugs are not recognized as treatment options for NDDs, the similarity of EZH1 GOF variants with those found in EZH2 associated cancers suggest a potential route for epigenetic recovery of EZH1 GOF using EZH1/2 inhibitors." (PMID 37433783, 2023). "In addition we found that EZH1 p.A678G is equivalent to the cancer-associated EZH2-p.A677G variant, which modifies the substrate preference of EZH2 leading to a change in H3K27me0 to me3 kinetics that results in increased H3K27me3 levels." (PMID 37433783, 2023). "EZH2 is specifically targeted by Tazemetostat (DB12887), which also inhibits EZH1, underscoring its specificity and therapeutic relevance in cancer treatment." (PMID 40074445, 2025). "Collectively, these findings reveal a coordinated role for EZH1-dependent H3K27me1 and DNA methylation in sustaining oncogenic transcriptional programs and provide strong rationale for advancing dual EZH1/2 inhibitors for combination epigenetic cancer therapy." (PMID 41000734, 2025). "EZH1/2 inhibitor valemetostat (DS-3201), used at two different doses and reported to be effective against other cancers, slightly reduced PEL cell survival." (PMID 38534772, 2024). "We have shown that the nuclear p85β stabilizes EZH1 and EZH2 in cancer cells with a PIK3CA E545K mutation." (PMID 35418124, 2022). "Valemetostat is a dual inhibitor of EZH1 and EZH2 that prevents trimethylation of H3K27, leading to altered gene expression patterns, which suppresses proliferation of EZH1/2-dependent cancer cells." (PMID 34944658, 2021). "EZH1 is a member of the Polycomb group protein complex which are important components for prevention of cancer stem cell development." (PMID 27494611, 2016). "Given the many ongoing clinical trials of EZH2 and EZH1/2 inhibitors in a variety of cancers including HCC38, the combined use of epigenetic therapeutic agents, such as UNC1999, may prove useful to treat patients with advanced HCC." (PMID 34725436, 2021). "Interestingly, the EZH2 homolog EZH1 has been proposed to form PRC2 complexes with similar functions, EZH1 is commonly down-regulated in cancer, which contradicts its involvement as a cell cycle promoting PRC2 subunit." (PMID 26110843, 2015). "A specific EZH2 inhibitor, Tazemetostat or EPZ-6438 (35-fold stronger inhibition of EZH2 than EZH1, and ~100 fold stronger than other methyltransferases) is an FDA-approved drug used in cancer therapy." (PMID 39703699, 2024). "Differently from 5-AZA, the inhibition of the EZH1/2 histone methyltransferase by DS-3201, reported to contribute to STAT3 activation in other cancers, slightly affected STAT3 phosphorylation or survival in PEL cells, either alone or in combination with AG490." (PMID 38534772, 2024). "Although others have also recently shown the superiority of dual EZH1/2 inhibitors such as VAL, the contribution of EZH1 to H3K27 methylation states in cancer and the mechanism behind this superiority remains unclear." (PMID 41000734, 2025). "In hepatocellular carcinoma, combined knockdown of EZH1 and EZH2 has shown greater tumor suppression than targeting EZH2 alone, suggesting that dual inhibitors could be more effective in certain cancers." (PMID 40042761, 2025). "While many cancer-specific alterations in PcG subunits are related to specific developmental pathways or cancer-specific phenotypes, some sets of paralogs are universally up and downregulated across multiple cancers, including EZH2/EZH1, RING1B/RING1A and (CBX2/CBX8)/(CBX6/CBX7)." (PMID 34617019, 2021). "Targeting the enzymatic SET domain of EZH1/2 is the most straightforward approach; however, drug-resistant mutant cancers, as well as cancers dependent on non-enzymatic PRC2 function, have necessitated alternate approaches to inhibit PRC2." (PMID 34617019, 2021).
cancer (continued). "The examined molecules include major class I and II histone deacetylases (HDACs), histone demethylases LSD1, JMJD2A and JMJD2D, histone methyltransferases EZH1, EZH2 and G9a, and DNA methyltransferase DNMT1, most of which have been shown to be deregulated in cancer cells." (PMID 29464084, 2018). "Additionally, therapies such as adoptive T cell therapy, immune checkpoint inhibitors, angiogenesis and tyrosine kinase inhibitors, EZH1/2 and BET inhibitors (targeting sex-specific epigenetic and X chromosome inactivation) show sex dimorphism in anti-cancer treatment." (PMID 40303343, 2025). "Additionally, the roles of PRC1 subunits and EZH1 proteins in inflammation and cancer are not fully understood." (PMID 40042761, 2025). "Unlike the other PRC2 subunits, which are involved in cancers and developmental syndromes, the implication of EZH1 in human development and disease is largely unknown." (PMID 37433783, 2023). "While many of the identified transcription factors were described as central to cancer development (including SMARCB1, MAZ, EZH1 and H2AFX), none had an established role in ES, likely due to the limited number of functional studies of this tumor type." (PMID 34359637, 2021). "Using the cancer cell line encyclopedia dataset (n = 1036 cell lines), we found very strong inverse correlations between expression of HDAC11 and many of the candidate genes, but not EZH1." (PMID 31519896, 2019).